CD4 (CD4 molecule)
Diseases named in the same sentence as CD4 in open-access papers (continued):
Sharing a sentence is not in itself a finding about the gene and the disease.
COVID-19 (continued). "Moreover, the numbers of plasma cells, naïve CD4 T cells, CD4 memory activated T cells, follicular helper T cells, gamma delta T cells, resting dendritic cells, and activated dendritic cells were higher in the normal group than in the COVID-19 group." (PMID 37278873, 2023). "This could be one of the reasons explaining why RTX + bendamustine–treated patients showed a higher propensity to develop more severe COVID-19, even if their percentage of Spike-specific CD4+ T-cell response was comparable to RTX + other chemotherapy–treated patients." (PMID 38106404, 2023). "Furthermore, SARS-CoV-2 specific-IFN-γ-producing CD8+ and CD4+ T-cell responses were detected in 35 and 36/37 of HD patients, respectively, indicating that mRNA COVID-19 vaccines induce a booster effect on both humoral and cellular immune responses in this immunocompromised group." (PMID 37111331, 2023). "Thus, CD4-mediated SARS-CoV-2 infection of T helper cells may contribute to a poor immune response in COVID-19 patients." (PMID 37523305, 2023). "On the other hand, in the severe forms of infection (critical COVID-19 and bacterial septic shock), patients shared immune patterns with upregulated single-cell transcriptome sequencing at the following levels: B cells, monocyte classical, CD4 and CD8 naïve T cells, and natural killers." (PMID 36979757, 2023). "In addition, there are other COVID-19 related factors expressed in CD4+ T cells." (PMID 37949890, 2023). "In addition, the inadequate CD8 T cell counts may partially transfer to the results observed increased CD4/CD8 ratio in patients with COVID-19." (PMID 37835544, 2023). "A recent study conducted among PLWH in Cape Town revealed that PLWH with CD4 count < 200 cells/μl were associated with COVID-19 death (aHR vs people living without HIV, 2.36 [95% CI, 1.47–3.78]; aHR vs PLWH with CD4 count ≥ 350 cells/μl, 1.97 [95% CI, 1.14–3.40])." (PMID 36855103, 2023). "In addition, inflammatory aggregates consisting of macrophages, multinucleated epithelioid cells, and CD4+ T cells that histologically resembled sarcoidosis-related granulomatous events were detected during postmortem examination of lung biopsies from COVID-19 patients." (PMID 38179278, 2023). "Furthermore, there is a subpopulation of CD4+ T cells with similar phenotype and functional capacity to Tfh cells in peripheral blood named circulating follicular helper T (cTfh) cells, which are also strongly driven following COVID-19 vaccination." (PMID 36969254, 2023). "Of note, in COVID-19 patients with pneumonia, the ability of CD4+ T cells to produce IL-17 in vitro is increased, which can enhance inflammatory response and activate neutrophils, suggesting that T cell activation in COVID-19 patients is significantly biased toward Th-17 functional phenotype." (PMID 37601070, 2023). "In contrast, a recent study from South Africa showed a significantly reduced frequency of Mtb-specific CD4 T cells in the peripheral blood of individuals with COVID-19, which supports the hypothesis that COVID-19 might increase the progression to TB disease in those with latent infection." (PMID 37386354, 2023). "The present results also showed that only 54.7% of PLHIV admitted in 2020, with available data, had CD4+ T-lymphocyte counts above 500 cells/μL, a condition that may have contributed to the finding of greater severity of COVID-19 among PLHIV compared to controls." (PMID 37331214, 2023). "In addition to humoral responses, cellular immunity contributes to protection against COVID-19 and recent evidence suggests that viral-vector and mRNA vaccines elicit long-lasting S-specific or nucleoprotein-specific CD4+ and CD8+ T cell responses, with broad cross-reactivity against VOCs29,30." (PMID 36781853, 2023).
COVID-19 (continued). "The higher expression of proinflammatory cytokines in COVID-19 patients, especially in severe cases, with the consumption of CD4+CD8+ T cells might result in aggravated inflammatory responses, the production of cytokine storms and clinical conditions worsening." (PMID 36836679, 2023). "In addition, cytokine levels are inversely correlated with the number of CD4+ and CD8+ T cells, B cells, and natural killer (NK) cells, manifesting as lymphopenia in the peripheral blood, causing an uncontrolled hyperinflammatory response in COVID-19." (PMID 37445296, 2023). "In summary, our study highlights a complex recovery of the immune system following severe COVID-19 with evidence of persistent activation of CD4+ and CD8+ T-cells, which may be bystander driven, and elevated levels of T-cell-related cytokines in the plasma of severe patients at 3 months." (PMID 37310006, 2023). "Additionally, recent research found that patients with COVID-19 had higher proportions of Tregs (characterized by the presence of CD3+ CD4+ CD25+ markers) and higher levels of FoxP3 expression by Tregs, which were associated with a poor prognosis of the disease." (PMID 36992283, 2023). "Study in Wuhan, China HIV positive patients investigated- 1701 Proportion of COVID-19 in PLWH- 0.6% (95% CI 0.2-1.0) Proportion of COVID-19 to the overall population in Wuhan- 0.6% Average CD4+ T lymphocyte count- >200 Average viral load- <20 copies Older PLWH had low CD4 cell count." (PMID 37288215, 2023). "However, higher expression of memory CD4 T cells compared to CD8 T cells might contribute to poor clinical outcomes observed in COVID-19 COPD patients." (PMID 36560586, 2022). "Cut-off values and ORs (95% CI) for the risk of developing severe/critical COVID-19 in the univariate and multivariate analyses for News-2, Ferritin, CRP and NLR (model 1), for the cytokines sCD25, IL1Ra and IL18 (model 2) and for activated CD4 and CD8, NK, Tc2 and EMRA CD8 (model 3)." (PMID 35425776, 2022). "In addition to the hypoxemia of COVID-19 patients, more and more studies have confirmed that COVID-19 patients tend to show declined lymphocyte, absolute number of T lymphocytes, CD4+T and CD8+ T cells decreased in nearly all the patients, and were markedly lower in severe cases." (PMID 35712114, 2022). "COVID-19 group demonstrated significantly increased tissue immunoexpression of Arginase-1 and IL-4 (p = 0.002 and p < 0.0001, respectively) and increased number of Perforin-1+ (p = 0.009), CD4+ (p = 0.009), CD68+ (p = 0.013), CD138+ (p < 0.0001) cells in comparison to the H1N1 group." (PMID 36430210, 2022). "Furthermore, we establish that male COVID-19 patients with a fatal outcome display a late coordinated depletion of circulating subsets of differentiated CD4+ T lymphocytes and monocytes, mirrored by a relative enrichment of undifferentiated CD4+ T cells and monocytes." (PMID 35351135, 2022). "Furthermore, in the recovered COVID-19 subjects with low antibody levels, their spike-specific CD4 T cells showed very little proliferative response in vitro, and in the small number of cells that did proliferate, they appeared to relatively highly express the Treg transcription factor Foxp3." (PMID 36544780, 2022). "Consequently, Q-VD may represent an attractive molecule for COVID-19 patients by preventing the apoptosis of both CD4 and CD8 T cells and increasing Th1 profiles." (PMID 35066575, 2022). "Studies comparing antibody and T cell responses generated against VOCs in COVID-19 convalescents and recipients of the Moderna and Pfizer-BioNTech vaccines showed variable degrees of impairment in antibody responses, but the preservation of CD4+ and CD8+ T cell responses." (PMID 35401519, 2022). "After immunization, the vaccine can induce CD8+ T cells and a variety of CD4+ T-cell subtypes that can weaken the symptoms of COVID-19 at the same time, indicating that the vaccine may play many other positive functions in addition to preventing SARS-CoV-2 infection." (PMID 35891267, 2022).
COVID-19 (continued). "Moreover, the CD4 to CD8 ratio might be a predictive biomarker for the effectiveness of COVID-19 vaccines in PLWH." (PMID 36532034, 2022). "While males may have a higher risk of developing severe COVID-19, we did not detect significant sex-based differences in acute CD4+ T cell responses, consistent with other reports." (PMID 35806161, 2022). "Consequently, preventing CD4 T-cell death might be a strategy for improving humoral response during the acute phase, thereby reducing COVID-19 pathogenicity." (PMID 36030261, 2022). "Studies have shown that PLWH might be at an increased risk of SARS-CoV-2 infection or COVID-19 mortality, especially those with a longer duration of HIV infection, comorbidities, lower CD4+ T lymphocyte count (CD4 count), or unsuppressed HIV viral load (HIV-VL)." (PMID 35791004, 2022). "Consequently, preventing CD4 T-cell death might be a strategy for improving humoral response during the acute phase, thereby reducing viral dissemination and COVID-19 pathogenicity and also specific immune memory." (PMID 36030261, 2022). "Moreover, we found a significant increase of AIM+ (both OX40+CD137+ and OX40+CD40L+) CD4+ T cells in moderate and severe COVID-19 patients in response to SARS-CoV-2 peptides (especially spike peptides) compared to pre-pandemic controls who are unexposed to SARS-CoV-2." (PMID 36248882, 2022). "Our findings also suggest that the persistence of activated and multi-functional SARS-CoV-2-specific CD4+ T cells is one of the hallmarks of immunity in recovered COVID-19 individuals and could possibly act as a correlate of protective immunity against re-infection." (PMID 35336918, 2022). "A meta-analysis stratifying the outcomes according to CD4 count would therefore make it possible to distinguish whether severely immunocompromised patients are less likely to present severe COVID-19 compare with patients on ARVs with a CD4 count above 200 cells/mm3." (PMID 35031068, 2022). "Indeed, we observed that the increase in the PCPhenoAge clock estimates for participants following COVID-19 was significantly related to the magnitude of changes in the percent of CD4 T cells, B cells, granulocytes, plasmablasts, exhausted T cells, CD8 naïve T cells, and CD4 naïve T cells." (PMID 35719387, 2022). "To determine whether SARS-CoV-2–associated TCRs used in our analyses are associated with functional CD4+ T cell responses, we enriched CD4+ T cells from PBMCs collected from 3 people in our convalescent cohort who were hospitalized and admitted to intensive care for treatment of COVID-19." (PMID 35439166, 2022). "Among the factors that may impede viral clearance of COVID-19 are decreases in the number of circulating NK cells, Th1 CD4+ T cells, pDCs, phagocytic neutrophils and monocytes, as well as the immunomodulatory properties of progesterone, which is elevated in pregnancy." (PMID 35955740, 2022). "Additionally, studies have shown that COVID-19 primarily affects CD4+ T and CD8+ T cells." (PMID 36016121, 2022). "However, an understanding of the complexities of immune memory to SARS-CoV-2 in an integrated manner is still rare, including the evaluation of antibody responses (and nAb), memory B cells, memory CD4+ or CD8 + T cell responses in a given population of COVID-19 convalescents." (PMID 35240947, 2022). "The analysis of T-helper differentiation in peripheral blood revealed a relative loss of ‘naïve’ CD4 T cells (with CD45RA+CD27+CCR7+CD95− phenotype) but a significant increase in the amount of EM2 (CD45RA−CD27−CCR7+) and EMRA (CD45RA+CD27−CCR7−) cells in COVID-19 patients compared to controls." (PMID 35632823, 2022). "In addition to this, most COVID-19 patients have a low number of CD4+ and CD8+ T lymphocytes." (PMID 35062298, 2022).
COVID-19 (continued). "CD4+ T cells have also been suggested to serve as a coordinator of cellular and humoral immunity in vaccinated individuals, as levels of CD4+ T cells after the first dose of a COVID-19 mRNA vaccine were predictive of post-second-dose humoral and CD8+ T cell responses." (PMID 35439166, 2022). "Moreover, patients with COVID-19 had significantly less central and effector memory CD4 T-cell subsets capable of IFNγ and TNFα co-expression in response to a polyclonal in vitro stimulation with PMA/Ionomycin mixture in comparison with the controls and COVID-19 convalescents." (PMID 35632823, 2022). "Vaccine-induced SARS-CoV-2–specific CD4+ T cells could pose as the main line of defense against COVID-19 in vaccinated individuals, since VOCs can evade neutralizing antibodies and SARS-CoV-2–specific CD8+ T cells are not invariably induced after vaccination at appreciable quantities." (PMID 35230977, 2022). "Moreover, studies on COVID-19 patients showed that antigen-specific CD4+ T cells could be detected as early as 2 to 4 days following symptom onset, and this early detection was associated with improved outcomes." (PMID 35955740, 2022). "Moreover, the balance between T cells of significantly different specificities may be the key to understand how CD4+ T cell dysregulation can determine the clinical outcomes of COVID-19." (PMID 35844575, 2022). "Also, CD4/CD8 ratio that is imbalanced in COVID-19 can restore by cobrotoxin." (PMID 35273645, 2022). "If patients received the Johnson and Johnson COVID-19 vaccine, then a second dose ideally with a mRNA COVID-19 vaccine at least 4 weeks after the first dose and a booster dose of a mRNA vaccine at least 2 months after the 2nd dose if CD4 < 200 cells/mm3 is recommended." (PMID 35456055, 2022). "Consequently, renal dysfunction found in COVID-19 patients, an immunocompromised state (reduced levels of CD4+ and CD8+ cells and increased cytokines circulation) may lead to the occurrence of mucormycosis." (PMID 35744726, 2022). "Moreover, chronological age was significantly associated with the inferred cell type proportional changes following COVID-19 for CD4+ T cells, plasmablasts, and CD4+ naïve T cells adding further support to our observed age-related COVID-19 shifts in specific immune cell type observations." (PMID 35719387, 2022). "Conversely, during the acute phase of SARS-CoV-2 infection, CD4+ T cells from the lungs of patients with COVID-19 did not increase Th17-associated genes, including RORC, IL17A, and IL17F, and CCR6 expression was significantly reduced in patients with severe COVID-19." (PMID 36146622, 2022). "Moreover, COVID-19 immunophenotyping studies revealed higher levels of autophagolysosome formation in CD4+ and CD8+ cells compared to CD14+ cells (p = 0.04 and p = 0.0007, respectively); however, the autophagy level in CD19+ cells was not higher as compared to CD14+ cells." (PMID 35711451, 2022). "Severe COVID-19 is associated with reduced CD4+ and CD8+ T cell immunity, but not B cell responses." (PMID 35004764, 2021). "In addition to showing that COVID-19 has decreased levels of CD4+ and CD8+ T cells, it has also been shown that the levels of CD4 + T cells expressing CD38− and HLA-DR−, and CD8+ T cells and CD4+PD-1+ T cells, were higher in the proportion of patients with severe COVID-19 compared to healthy people." (PMID 34359987, 2021). "As the known CXCR3 ligands, CXCL9, CXCL10, and CXCL11, are predominantly induced by IFNγ, the presence of this CXCR3-expressing CD11b+CD14+ monocyte subset may be mechanistically related to the synchronous increase in the IFNγ-producing CD4+ T cell subset in our convalescent COVID-19 cohort." (PMID 34113347, 2021). "Moreover, gene expression analyses in the CD4+ T cells from COVID-19 patients revealed a decrease in IL-2 transcripts in severe COVID-19 cases compared to mild cases, which could be another reason for decreasing Treg cells." (PMID 35126355, 2021).
COVID-19 (continued). "Studies of acute and convalescent COVID-19 patients have observed that T cell responses are associated with reduced disease, suggesting that SARS-CoV-2-specific CD4+ T cell and CD8+ T cell responses may be important for control and resolution of primary SARS-CoV-2 infection." (PMID 33408181, 2021). "Therefore, future studies might consider assessing how the association between HIV and severe COVID-19 outcomes is moderated or mediated by comorbidities, HIV viral load, CD4 count, and ARV therapy." (PMID 33737527, 2021). "However, there is insufficient evidence as to whether CD4+T cells can predict the prognosis in patients with COVID-19." (PMID 33435865, 2021). "We checked if MILD COVID-19 patient-recovered exosomes could enhance CD4+ T-cell activation." (PMID 35111156, 2021). "Approximately 20% of HIV patients with severe CD4+ T cell deficiency develop an IRIS after commencing ART, which presents at a median time of 10-16 days for TB-IRIS, while approximately 20% of people with symptomatic SARS-CoV-2 infection develop severe COVID-19 at about 10 days after symptom onset." (PMID 33841434, 2021). "Although we cannot rule out that significant differences in cell populations might not determine the disease severity, SARS-CoV-2-specific CD4+ T cells were strongly linked with milder COVID-19, unlike antibodies and CD8+ T cell numbers." (PMID 34434199, 2021). "The dysregulated inflammation and immune response in COVID-19 patients may be mainly due to lymphopenia, especially CD4 + and CD8 + T lymphopenia, activation of complement system, extensive inflammation, production of cytokine storm, and eventually severe multi-organ injury." (PMID 33664741, 2021). "While this may partly be due to the well-described lymphopenia in severe COVID-19, which is prognostic of poor outcomes, about half of patients with low CD4 counts during admission were either new HIV diagnoses or had previous immunosuppression, viremia, or no recent ART." (PMID 32860699, 2021). "However, although not statistically significant, the proportion of activated M. tuberculosis–specific CD4+ T cells tended to be higher in COVID-19–coinfected patients compared with the non–COVID-19 group (median: 74 %, IQR: 49%–94% vs. 57.7%, IQR: 50%–77%, respectively)." (PMID 33945513, 2021). "In addition, some COVID-19 patients develop other complications such as diabetes, which cause CD4+ T cells to differentiate into Th1 and Th17 rather than into Tregs, leading to diminished immunosuppression." (PMID 34631206, 2021). "Thus, production of robust, long-lived humoral immunity following COVID-19 vaccination even in the setting of HIV-induced CD4 depletion and immune exhaustion may be possible." (PMID 34992610, 2021). "Given the divergent role of CD4+ T cells in regulating both humoral immunity and cellular immunity, we suspect that the relatively mild disease severity of these COVID-19 patients included in our study may benefit from a stronger CD4+ T cell response to SARS-CoV-2." (PMID 34805136, 2021). "In addition, there is growing evidence that there may be a role of HIV-associated immune impairment, in particular lower CD4+ T-cell counts, with susceptibility to SARS-CoV-2 infection or COVID-19 severity." (PMID 34992610, 2021). "However, although a decline in CD4+/CD8+ ratio may serve as a useful metric in analyzing of the derangement in immune responses in patients with severe COVID-19, further study with larger sample sizes is highly recommended." (PMID 33937149, 2021). "CD4+ T helper has been implicated in the pathogenesis that leads to the inflammation process, as well as being affected by SARS-CoV-2 replication, diminishing the T follicular helper cells, contributing to the loss of antibodies, and reduction of IFN-γ production in COVID-19 patients." (PMID 34571855, 2021). "However, we observed slightly higher ratios of CD4 to CD8 in COVID-19 samples." (PMID 34441292, 2021).